TMPRSS3 (transmembrane serine protease 3)
Description:
Probable serine protease that plays a role in hearing. Acts as a permissive factor for cochlear hair cell survival and activation at the onset of hearing and is required for saccular hair cell survival (By similarity). Activates ENaC (in vitro).
Synonyms: ECHOS1; TADG12; DFNB10; DFNB8
Tractability: Antibody: UniProt predicts a signal peptide or a membrane-spanning region. PROTAC: ubiquitination databases record sites on it.
Gene: Protein-coding gene on chromosome 21 (42,371,840 to 42,396,119, reverse strand). Ensembl gene ENSG00000160183.
Subcellular location: Endoplasmic reticulum membrane
Gene Ontology:
Molecular function: sodium channel regulator activity; serine-type endopeptidase activity; serine-type peptidase activity
Biological process: intracellular sodium ion homeostasis; protein processing; proteolysis; sensory perception of sound
Cellular component: endoplasmic reticulum; endoplasmic reticulum membrane; membrane; neuronal cell body
Genetic constraint (gnomAD): Loss-of-function variants: 53 observed, 60.25 expected, observed/expected ratio (o/e) 0.88, 90% interval 0.7 to 1.11. The upper end of that interval is the gene's LOEUF score, 1.11, which puts it in group 4 of 6, group 1 being the genes least tolerant of losing a copy. Missense variants: 586 observed, 601.97 expected, observed/expected ratio (o/e) 0.97, 90% interval 0.91 to 1.04. Synonymous variants: 253 observed, 247.85 expected, observed/expected ratio (o/e) 1.02, 90% interval 0.92 to 1.13.
Gene-disease validity (ClinGen):
ClinGen rates the evidence that TMPRSS3 causes each of these diseases.
nonsyndromic genetic hearing loss (autosomal recessive): Definitive. A disease characterized by hearing loss that is not part of a larger syndrome.
Homologues: Orthologues: chimpanzee TMPRSS3 (99% identical), macaque TMPRSS3 (97% identical), dog TMPRSS3 (90% identical), mouse Tmprss3 (89% identical), rat Tmprss3 (89% identical), pig TMPRSS3 (89% identical), guinea pig TMPRSS3 (88% identical), tropical clawed frog TMPRSS3 (55% identical), zebrafish tmprss3a (48% identical), zebrafish tmprss3b (35% identical), Drosophila melanogaster Sb (28% identical), Drosophila melanogaster CG17242 (11% identical). Paralogues in human: TMPRSS2 (38% identical), TMPRSS13 (32% identical), TMPRSS6 (32% identical), TMPRSS15 (31% identical), HPN (30% identical), ST14 (30% identical), TMPRSS7 (29% identical), TMPRSS11F (28% identical), TMPRSS5 (28% identical), TMPRSS11D (27% identical), TMPRSS11E (27% identical), TMPRSS9 (26% identical), and 5 more.
Diseases named in the same sentence as TMPRSS3 in open-access papers:
TMPRSS3 is named in the same sentence as 42 diseases in open-access papers, as found by Europe PMC text mining. Sharing a sentence is not in itself a finding about the gene and the disease. The quoted sentences say what the papers report.
deafness (40 papers, 2004 to 2025). An inherited or acquired condition characterized by the complete loss of the ability to hear from one or both ears. "The 15 associations included a missense lead variant in TMPRSS3, a known cause of Mendelian hearing loss, adding to the tally of Mendelian deafness genes (EYA4, CDH23, TRIOBP) showing common coding-variant associations with hearing loss in adult humans." (PMID 35661827, 2022). "The other 6 variants were associated with recessive forms of deafness (TMPRSS3, GPSM2, BDP1, EPS8, EPS8L2, and PCDH15)." (PMID 33809266, 2021). "Seven missense TMPRSS3 mutants (D103G, R109W, C194F, R216L, W251C, P404L, and C407R) associated with deafness in humans were unable to activate the ENaC." (PMID 33820827, 2021). "A common feature of patients with TMPRSS3 mutations is progressive HL beginning in high frequencies and often leading to partial or complete deafness." (PMID 34795337, 2021). "TMPRSS3 was the causal gene of autosomal recessive deafness (type 8), and 23 pathogenic variants in this gene have been identified in ClinVar." (PMID 32682410, 2020). "In this study, 48.5% (16/33) families were detected the pathogenic variants in eight known deafness genes, including 10 novel variants identified in TMPRSS3 (MIM 605551), MYO15A (MIM 602666), TMC1 (MIM 606706), ADGRV1 (MIM 602851), and PTPRQ (MIM 603317)." (PMID 31379920, 2019). "Combining the data from this study and our previous work, we determined that mutations in TMPRSS3 are a pathogenic cause of deafness in 7 of 151 (4.6%) Chinese families with ARNSHL." (PMID 28695016, 2017). "We performed targeted re-sequencing to identify the genetic etiology of early-onset postlingual deafness and encountered a frequent TMPRSS3 allele harboring two variants in a cis configuration." (PMID 29072634, 2017). "Many TMPRSS3 mutations have been reported as pathogenic mutations for inheritable deafness, including an 8-bp deletion, insertion of multiple beta-satellite repeat units, and a frameshift mutation." (PMID 25474651, 2014). "In this study, we document the mutant alleles of TMPRSS3 segregating in a large family from Newfoundland and in additional Pakistani families with nonsyndromic, recessive deafness." (PMID 15447792, 2004). "We previously reported pathogenic TMPRSS3 mutations in four out of a total of 159 Pakistani families segregating profound congenital recessive deafness." (PMID 15447792, 2004). "To determine the contribution of TMPRSS3 mutations to recessive deafness in Pakistan, we screened an additional 290 Pakistani families for linkage to the DFNB8/B10 locus." (PMID 15447792, 2004). "TMPRSS3 mutations account for hearing loss in 1.8% (8 of 449) of Pakistani families segregating deafness as an autosomal recessive trait." (PMID 15447792, 2004). "The previously developed Tmprss3-null mouse model (Tmprss3Y260X/Y260X) shows rapid degeneration of cochlear hair cells (HCs) beginning at the onset of hearing at P12, leading to compete loss of HCs by P14 and resulting in profound deafness." (PMID 40674144, 2025). "There are 41 reported TMPRSS3 mutations identified as causing deafness." (PMID 39442262, 2024). "Overview of the part of deafness-associated mutations in TMPRSS3." (PMID 36568422, 2022). "There are reports of 41 TMPRSS3 mutations identified as causing deafness." (PMID 36529647, 2022). "Additionally, two likely pathogenic variants in TMPRSS3 (NM_024022.2), a gene known for being causative of autosomal recessive deafness (MIM#: 601072, ORPHA: 90636), were identified in the proband." (PMID 35052694, 2021). "To date, only four CNV's in TMPRSS3 have been linked to deafness." (PMID 31016883, 2019).
deafness (continued). "Results of this study, while seriously underpowered, provide evidence that pathogenic variants in TMPRSS3 could help us refine our understanding of the molecular physiology of hearing and deafness." (PMID 30242206, 2018). "Three subjects had pathogenic genetic variants in TMPRSS3 causing DFNB8 deafness (TMPRSS3 Group)." (PMID 30242206, 2018). "This mutation is located in the highly conserved catalytic serine protease domain and probably causes the disturbance of the proteolytic function of TMPRSS3, which may explain the underlying molecular etiology of deafness." (PMID 28246597, 2017). "Moreover, the mutation pR109W in the LDLRA domain of TMPRSS3 has been detected in multiple Asian familiar deafness cases." (PMID 25474651, 2014). "Pathogenic deafness mutations in TMPRSS3 identified in previous studies." (PMID 25474651, 2014). "Our results provided a new example of prelingual deafness caused by a TMPRSS3 mutation." (PMID 25474651, 2014). "Hence, it is unlikely that the deafness of individuals IV:10 and VI:1 is due to cryptic TMPRSS3 mutations." (PMID 15447792, 2004). "In these populations, TMPRSS3 mutations might still be a significant cause of deafness." (PMID 28695016, 2017). "Mutations in TMPRSS3 can result in two distinct phenotypes: prelingual (DFNB10) and delayed onset and postlingual (DFNB8) deafness." (PMID 38525683, 2024). "All seven of these families have variants in seven different known deafness genes, LRTOMT, LHFPL5, TMPRSS3, OTOF, MYO15A, ESRRB, and KCNE1." (PMID 31835641, 2019). "Mutations in the TMPRSS3 (transmembrane protease, serine 3) gene cause prelingual (DFNB10) or postlingual (DFNB8) deafness." (PMID 28695016, 2017). "Although TMPRSS3 mutations seem to be less common than GJB2 mutations, TMPRSS3 mutations lead to inheritable deafness, especially when common GJB2, SLC26A4 and 12S rRNA mutations are excluded." (PMID 25474651, 2014). "The family from Pakistan that originally defined the DFNB8 locus was reported to have childhood onset hearing impairment, while all remaining families segregating TMPRSS3 mutations have pre-lingual deafness." (PMID 15447792, 2004). "In this study, we searched for mutant alleles of TMPRSS3 in families from Pakistan and Newfoundland with recessive deafness co-segregating with DFNB8/B10 linked haplotypes and also more thoroughly characterized the genomic structure of TMPRSS3." (PMID 15447792, 2004). "The most frequent causative deafness gene was TMC1 (DFNA36) (3 cases), followed by the next tier of genes (2 cases each) (CDH23, COCH, SLC26A4, TMPRSS3, ATP1A3), and the genes that were detected only once (ACTG1, GJB2, ILDR1, MYO7A, MYO15A, NF2, NLRP3 and SERPNB6)." (PMID 32238869, 2020). "The known deafness genes with variants detected in this study were GJB2 (MIM 121011; 21.2%), TMPRSS3 (MIM 605551; 6.1%), MYO15A (MIM 602666; 6.1%), TMC1 (MIM 606706; 3%), ADGRV1 (MIM 602851; 3%), PTPRQ (MIM 603317; 3%), SLC26A4 (MIM 605646; 3%), and OTOF (MIM 603681; 3%)." (PMID 31379920, 2019). "Expression in both the spiral ganglion and the cochlear sensory organ indicates a possible functional role in both tissues; however, in vitro studies have failed to clarify the mechanism by which TMPRSS3 causes deafness." (PMID 30242206, 2018). "In the future, this approach may be used to test the feasibility of treating other inherited deafness cases in which the SV is the predominant site affected (e.g. mutations in KCNE1, CCDC50, DFNA5, MYH14, TFCP2L3, TMPRSS3 genes)." (PMID 26084842, 2015).
deafness (continued). "We and others have previously shown that, unlike other forms of genetic HL, TMPRSS3-related HL is associated with variable speech perception outcomes after cochlear implantation in adults and is correlated with duration of deafness, possibly due to reduced spiral ganglion neuron (SGN) function." (PMID 40674144, 2025). "Twelve homozygous mutations in known deafness genes, of which eight are novel, were identified in 12 families: MYO15A-p.Q1425X, -p.S1481P, -p.A1551D; LOXHD1-p.R1494X, -p.E955X; GIPC3-p.H170N; ILDR1-p.Q274X; MYO7A-p.G2163S; TECTA-p.Y1737C; TMC1-p.S530X; TMPRSS3-p.F13Lfs*10; TRIOBP-p.R785Sfs*50." (PMID 23226338, 2012). "TMPRSS3, MYO15A, GJB2, SLC26A4 were found to be responsible for deafness in autosomal recessive or sporadic families." (PMID 23967202, 2013). "This physically connected network contains two known non-syndromic deafness genes MYO6 (MIM ID 600970) and TMPRSS3 (MIM ID 605511)." (PMID 21980309, 2011). "In the current study, three known deafness genes (GJB2, TMPRSS3, and MYO15A) were detected in several pedigrees, suggesting that the strategy of proband-WES can be successfully applied to search for novel ARNSHL genes shared by multiple families with similar phenotype." (PMID 31379920, 2019). "TMPRSS3, MYO15A, GJB2, SLC26A4 were found to be responsible for deafness in autosomal recessive or sporadic families, while TECTA, WFS1, MYH9, EYA1, COL4A5 and COL11A1 were identified as the responsible genes for deafness in autosomal dominant families." (PMID 23967202, 2013).
hearing loss (40 papers, 2004 to 2026). "Intriguingly, splice-site variants led to a more severe impairment of enzymatic activity compared to missense variants, providing molecular evidence for the considerable genotype-phenotype heterogeneity observed in TMPRSS3-associated hearing loss." (PMID 41923883, 2026). "One among them, responsible for both, childhood-onset progressive (DFNB8) and congenital/prelingual (DFNB10) forms of non-syndromic hearing loss is TMPRSS3, which encodes a transmembrane protein with extracellular serine protease domain." (PMID 41312438, 2025). "TMPRSS3-related hearing loss presents challenges in correlating genotypic variants with clinical phenotypes due to the small sample sizes of previous studies." (PMID 38691166, 2024). "In this study, we aimed to investigate the clinical and genetic features of TMPRSS3-related hearing loss by collecting data from a large, international cohort of affected individuals." (PMID 38691166, 2024). "Our results provide new insights into the genetic basis of TMPRSS3-related hearing loss, which has implications for genetic counseling and the timing of targeted therapies currently in development." (PMID 38691166, 2024). "Here, we tested combinations of AAVs and promoters to deliver Tmprss3, mutations in which are associated with hearing loss in humans." (PMID 37663645, 2023). "This is likely related to the general progressive nature of TMPRSS3-associated hearing loss, leading to a choice for a longer electrode to stimulate low-frequencies." (PMID 38102706, 2023). "The phenotype of the patient’s hearing loss is highly specific for TMPRSS3-related hearing loss (DFNB8/10)." (PMID 37086329, 2023). "Missense mutations of TMPRSS3 cause variable onset and degrees of sensorineural hearing loss, leading to prelingual (DFNB10) or postlingual (DFNB8) ARNSD." (PMID 37663645, 2023). "This is in keeping with recent literature evaluating the association of genetic diagnosis for childhood-onset hearing loss on cochlear implant outcomes, in which patients with a TMPRSS3 mutation demonstrated some of the highest speech perception outcomes." (PMID 37713394, 2023). "Since subjects with TMPRSS3-associated hearing loss have, in general, sufficient residual hearing in the lower frequencies, the round window approach was more frequently used since this technique is supposed to lead to better HP." (PMID 38102706, 2023). "While the function of the TMPRSS3 gene in the auditory system is not fully understood, its alteration has been linked with non-syndromic genetic hearing loss." (PMID 34868270, 2021). "The hearing impairment in families with mutations in the TMPRSS3 gene has a prelingual to postlingual onset." (PMID 34795337, 2021). "Overview of TMPRSS3 variants resulting in non-syndromic hearing loss, including those identified in the present study." (PMID 34868270, 2021). "For example, somatic overexpression of TMPRSS3, a transmembrane serine protease, mostly known for its association with non-syndromic hearing loss, was previously reported to be associated with breast, ovarian, and pancreatic cancers." (PMID 32371905, 2020). "We have previously shown that the transmembrane serine protease is tightly correlated with the auditory phenotype of hearing loss subjects carrying autosomal recessive mutations of TMPRSS3." (PMID 29072634, 2017). "It has been reported that mutations in different domains of TMPRSS3 result in various hearing impairment phenotypes, likely due to the distinct influence on protease activity of different mutations." (PMID 28695016, 2017). "We concluded that different combinations of TMPRSS3 mutations led to different hearing impairment phenotypes (DFNB8/DFNB10) in this family." (PMID 28246597, 2017). "A novel homozygous missense mutation was identified in TMPRSS3 (MIM_605511), c.726C>G (p.Cys242Trp) that co-segregated with hearing impairment in family DFR24 and was predicted to be probably damaging by Polyphen2 and deleterious by SIFT." (PMID 24949729, 2014).
hearing loss (continued). "We also screened TMPRSS3 for mutations in a large kindred from Newfoundland, Canada segregating hearing loss linked to markers for DFNB8/B10 and surprisingly found two different mutant alleles." (PMID 15447792, 2004). "Mutations of TMPRSS3 contribute to hearing loss in many communities worldwide and account for 1.8% (8 of 449) of Pakistani families segregating congenital deafness as an autosomal recessive trait." (PMID 15447792, 2004). "In patients with bialleleic TMPRSS3 mutations, an intracochlear electrode was employed to electrically stimulate the neurons in the ganglion spirale, which revealed a smaller auditory nerve response compared to patients with other hearing loss etiologies." (PMID 41509903, 2026). "Similar variability has been described in Tmprss3 mouse models, where both hair cell and neuronal defects occur, which may explain the combined sensory-neuronal phenotype in human TMPRSS3-associated hearing loss." (PMID 41509903, 2026). "Pathogenic variants in the gene TMPRSS3 are a common cause of hearing loss in humans, although the causal mechanisms remain unknown." (PMID 40674144, 2025). "However, investigating the genotype–phenotype correlations of TMPRSS3 variants with hearing loss has been challenging due to the relatively small number of cases seen in most centers." (PMID 38691166, 2024). "Variations in TMPRSS3 are an important cause of genetic hearing loss." (PMID 38691166, 2024). "As we continue to build larger cohorts of individuals with TMPRSS3-related hearing loss, we will increase our predictive power and our ability to understand the therapeutic window and best approaches for the treatment of individuals with TMPRSS3 hearing loss." (PMID 38691166, 2024). "Encoding a type III transmembrane serine protease, the TMPRSS3 gene has had 87 different variants described associated with non-syndromic hearing loss, with native gene expression seen in inner hair cells, spiral ganglion neurons, stria vascularis, and the cochlear aqueduct." (PMID 37713394, 2023). "Additionally, cohort data from 18 patients, and their families, with a positive result for TMPRSS3-associated hearing loss were analyzed." (PMID 34868270, 2021). "Mutations in TMPRSS3 have previously been described to cause autosomal recessive progressive hearing impairment with postlingual onset (DFNB8) as well as severe-to-profound prelingual hearing impairment (DFNB10)." (PMID 28246597, 2017). "To date, several genetic studies of TMPRSS3-related hearing impairment have been conducted, and 31 recessive mutations in TMPRSS3, including p.Ala179Thr, which was identified in a Tibetan family from China, were shown to be associated with ARNSHI in more than 14 ethnic groups worldwide." (PMID 28246597, 2017). "Several other studies have also found a variety of TMPRSS3 mutations in patients with hearing loss." (PMID 25474651, 2014). "This potential may be similarly applied to treating different progressive forms of hearing loss, where timely intervention is crucial to prevent irreversible damage, such as TMPRSS3-related hearing loss or the EPS8 model, where EPS8 expression could not be rescued after P2." (PMID 40859056, 2025). "In Saudi Arabia, several gene mutations (e.g., GIPC3, ILDR1, W77R, MYO15A, TMC1, TMPRSS3, and DFNB67) have been identified in families and are associated with childhood hearing loss." (PMID 40918669, 2025). "This research proposed new genes associated with hearing loss, such as COL9A3 and TMPRSS3, and highlighted the impact of both common and rare variants on the risk of hearing loss." (PMID 40971385, 2025). "More than 70% of genetic hearing loss is attributed to autosomal recessive, nonsyndromic deafness (ARNSD) mutations, up to 10% of which are caused by transmembrane protease serine 3 (TMPRSS3) mutations." (PMID 37663645, 2023). "TMPRSS3 mutations cause DFNB8 and DFNB10 and are found in up to 11% of patients with sensorineural hearing loss." (PMID 37663645, 2023).